TRPA1 (transient receptor potential cation channel subfamily A member 1)
Diseases named in the same sentence as TRPA1 in open-access papers (continued):
Sharing a sentence is not in itself a finding about the gene and the disease.
allergic asthma (6 papers, 2016 to 2023). A asthma with a basis in a pathological type I hypersensitivity reaction. "In the ovalbumin model of allergic asthma, TRPA1 has been reported to promote the release of inflammatory factors, mediate peripheral blood eosinophilia, increase leukocyte influx to the lungs and to increase airway hyperreactivity." (PMID 37386145, 2023). "In humans, biopharmaceutical companies have performed early-phase clinical trials investigating the effectiveness of TRPA1 antagonism in other clinical conditions, such as neuropathic pain and allergic asthma." (PMID 36733462, 2023). "TRPA1 has been shown to mediate asthmatic inflammation and hyperresponsiveness in models of allergic asthma." (PMID 37386145, 2023). "It is also possible that the suppressive effect of IL-4 on the functional expression of TRPA1 is a compensation mechanism aiming to limit inflammation and symptoms in allergic asthma." (PMID 37386145, 2023). "The current study aimed to evaluate the efficacy of the novel TRPA1 antagonist BI01305834 in guinea-pig models of allergic asthma." (PMID 33557843, 2021). "In a murine model of allergic asthma, TRPA1 in sensory neurons mediated leukocyte infiltration and increased pulmonary mucus production and airway hyperreactivity, supposedly through the release of neuropeptides such as CGRP and SP12." (PMID 27356469, 2016). "Conversely, in Th2-type conditions–such as in allergic asthma–response to TRPA1 antagonist therapy might be more limited, as the channel would already be moderately downregulated/desensitized." (PMID 37386145, 2023). "Furthermore, TRPA1 antagonist may be beneficial in treatment-resistant and non-allergic asthma as well, as cough responses are shown to be unrelated to AHR, airflow obstruction and treatment with inhaled corticosteroid." (PMID 33557843, 2021). "As an effect of TRPA1 antagonism on the AHR, EAR and LAR was observed in the guinea pig in vivo model of allergic asthma, we set out to further investigate this mechanism using lung slices and tracheal strips of allergen sensitized guinea pigs." (PMID 33557843, 2021). "TRPV1,but not TRPA1, KOs developed an attenuated allergic asthma phenotype although these effects failed to reach statistical significance." (PMID 27255083, 2016).
allergic rhinitis (6 papers, 2015 to 2026). Inflammation of the nasal mucous membranes caused by an IgE-mediated response to external allergens. "A recent study showed increased level of TRPA1 mRNA in subjects with rhinitis compared to normal controls (p = 0.03) suggesting potential involvement of TRPA1 in allergic rhinitis." (PMID 27827953, 2016).
contact dermatitis (6 papers, 2015 to 2023). An inflammatory skin condition caused by direct contact between the skin and either an irritating substance or an allergen. "It seems evident that TRPA1 not only serves as a sensor for pruritogens, but is also essential for maintaining skin inflammation, as shown in AD and contact dermatitis models in which treatment with TRPA1 inhibitors reduces skin swelling, epidermal water loss and leukocyte infiltration." (PMID 35873682, 2022). "In addition, acute administration of TRPA1 antagonists (within 30 min to 5 h after treatment) significantly inhibited inflammatory-mediated itch as well as in murine models of contact dermatitis." (PMID 30204499, 2019). "Additionally, many contact dermatitis reactions are TRPA1 mediated." (PMID 33193423, 2020). "In both acute and chronic models of murine contact dermatitis, symptoms of ACD were significantly decreased with both pharmacological inhibition as well as genetic ablation of TRPA1." (PMID 33193423, 2020). "Our data provided the first evidence that both TRPA1 and TRPV1 channels are critical mediators of persistent itch in the mouse model of SADBE-induced contact dermatitis, which is independent of the lymphocyte-mediated immunity." (PMID 29081531, 2017).
glioblastoma (6 papers, 2021 to 2025). The most malignant astrocytic tumor (WHO grade IV). "Consistently, an independent study showed that hypoxia increased TRPA1-dependent membrane currents in another human glioblastoma cell line, i.e., DBTRG, thereby inducing cytosolic Ca2+ overload, mitochondrial depolarization, caspase-3 and caspase-9 activation, and apoptosis." (PMID 37174661, 2023). "Conversely, preliminary evidence suggested that TRPA1 activation led to more protracted (and pervasive) Ca2+ elevations in OSCC and glioblastoma, thereby resulting in cancer cell apoptosis." (PMID 37174661, 2023). "Its complex reactive cysteine residue profile allows TRPA1 to sense H2O2-induced mitochondrial damage and apoptosis and may have a therapeutic role in TMZ-resistant glioblastoma." (PMID 39770499, 2024). "Conversely, stimulating TRPA1-mediated Ca2+ entry could represent a valuable tool to sensitize ROS-dependent cytosolic Ca2+ overload and apoptosis in OSCC, glioblastoma, and colorectal carcinoma." (PMID 37174661, 2023). "Conversely, TRPA1-mediated increase in intracellular Ca2+ concentration ([Ca2+]i) supports H2O2-induced mitochondrial damage and apoptosis in other types of solid malignancies, such as glioblastoma multiforme and human oral squamous cell carcinoma (OSCC)." (PMID 37393347, 2023). "Cancers in which TRPA1 is significantly underexpressed, and therefore may act as a tumor suppressor, are bladder urothelial carcinoma (BLCA), colon adenocarcinoma (COAD), kidney chromophobe (KICH), glioblastoma multiforme (GBM) and rectum adenocarcinoma (READ)." (PMID 39770499, 2024).
oral cancer (6 papers, 2015 to 2025). "Trpv4 was more highly expressed than transient receptor potential cation channel subfamily A member 1 (Trpa1) and transient receptor potential cation channel subfamily V member 1 (Trpv1), channels associated with oral cancer pain in neurons." (PMID 40144515, 2025). "Both TRPV1 and TRPA1 have been implicated in oral cancer and other pain syndromes." (PMID 36368973, 2022). "In preclinical cancer models, expression of TRPV1 and TRPA1 is increased in the trigeminal or dorsal root ganglia, including in oral cancer models." (PMID 36368973, 2022). "TRPA1 is the focus of research in the context of oral cancer (NCT05024383)." (PMID 40813985, 2025). "Studies are under way to quantify sensitivity of oral cancer patients to TRPA1 agonists." (PMID 36368973, 2022). "Accordingly, we tested the novel hypothesis that oral squamous cell carcinomas release certain oxidized lipids that activate TRPV1 and TRPA1 on sensory neurons, contributing to the development of oral cancer pain." (PMID 26007300, 2015). "We therefore hypothesize that oral squamous cell carcinomas release certain lipids that activate TRPV1 and/or TRPA1 on sensory neurons, contributing to the development of oral cancer pain." (PMID 26007300, 2015). "Patients with oral cancer have much higher levels of salivary linoleic acid and arachidonic acid, which activate TRPV1 and/or TRPA1 on sensory neurons and contribute to oral cancer pain." (PMID 40661938, 2025). "A more nuanced understanding of the contribution of chemical sensitivity, and the role of specific receptors and ion channels to oral cancer pain in patients might be obtained by assessing sensitivity to both TRPV1 and TRPA1." (PMID 36368973, 2022). "Oral cancer pain has been attributed to release from the cancer and/or cells of the cancer microenvironment of soluble mediators and extracellular vesicles carrying pain mediators with potential to sensitize TRPV1 and TRPA1 on sensory neurons." (PMID 36368973, 2022).
pancreatic cancer (6 papers, 2013 to 2024). "The transcriptional level of TRPA1 was significantly associated with the stage of pancreatic cancer, with increased expression at a higher stage." (PMID 36012311, 2022). "TRPA1 is overexpressed in pancreatic cancer, and blocking TRPA1 using cannabidiol suppresses tumor growth and reduces metastasis to the lungs." (PMID 37189782, 2023). "In this study, we found that TRPA1 expression was higher in pancreatic cancer tissues, which correlated with our previous results on PDAC cell lines." (PMID 36012311, 2022). "There are no reports on TRPA1 channel in PDAC, but the analysis of the Cancer Genome Atlas database reveals that TRPA1 is expressed in several patients with pancreatic cancer." (PMID 33479347, 2021). "The stimulatory effects of Cd were confirmed in TRPA1-expressing rat pancreatic cancer cells (RIN-14B)." (PMID 23448290, 2013). "Relevant information on the impact of TRPA1 on Pancreatic cancer is relatively limited." (PMID 37039840, 2023). "Next, we used UCSC Xena to explore the expression levels of TRPV6, TRPA1, TCAF1, TCAF2, and TRPM8 in pancreatic cancer (n = 178) and in normal pancreatic tissue (n = 167)." (PMID 36012311, 2022). "First, we queried GEPIA to explore the relationship between the TRPV6, TRPA1, TRPM8, TCAF1, and TCAF2 mRNA expressions and sub-stages in pancreatic cancer samples, compared to the control (normal subjects)." (PMID 36012311, 2022). "First, using the GEPIA web platform as a bioinformatic tool, we explored the transcriptional levels of TRPV6, TRPA1, TRPM8, TCAF1, and TCAF2 in pancreatic cancer (n = 179) and normal pancreatic tissues (n = 171)." (PMID 36012311, 2022). "Consistent with the GEPIA results, the expression levels of TRPA1, TRPM8, TCAF1, and TCAF2 were significantly higher in pancreatic cancer tissue (p < 0.001), and TRPV6 expression was significantly lower in pancreatic cancer tissue compared to normal tissues (p < 0.001)." (PMID 36012311, 2022).
Parkinson disease (6 papers, 2021 to 2025). A progressive degenerative disorder of the central nervous system characterized by loss of dopamine producing neurons in the substantia nigra and the presence of Lewy bodies in the substantia nigra and locus coeruleus. "In this study, we identify the expression of Parkinson’s disease-related DJ-1 in nociceptors and its role in prodromal pain and peripheral neuropathy through TRPA1 modulation." (PMID 39486088, 2025). "However, to date, the TRPA1 channel has not been linked with NCS-1, although some of the most essential functions of TRPA1 appear to require a close relationship with this Ca2+ sensor, such as memory, neuronal survival, cell death, Parkinson’s disease, CIPN, and cancer." (PMID 38564162, 2024). "Thus, it is tempting to speculate that TRPA1 could provide a mechanistic framework for improved treatment of prodromal pain and peripheral neuropathy in Parkinson’s disease, which is currently limited owing, in part, to a lack of understanding of its underlying mechanisms." (PMID 39486088, 2025).
pyrexia (6 papers, 2011 to 2020). "The trpA1 is closely associated with high temperature sensing and also increasing high-temperature tolerance, the painless is responsible for rapid acclimation to high temperature, and the pyrexia plays an important role in protecting T. castaneum adults from acute heat stress." (PMID 28786992, 2017). "In other insects such as T. castaneum, TRPA1, painless, and pyrexia work in a similar manner to mediate sensation of different ranges of high temperatures, heat tolerance, and acclimation." (PMID 32823776, 2020). "There are three TRPA channels, including TRPA1, painless, and pyrexia, involved in detection and avoidance of high temperatures in D. melanogaster." (PMID 32823776, 2020). "This analysis revealed strong evidence that five of our 13 TRP candidates belong to the TRPA family, including TRPA1, painless and three pyrexia-like sequences." (PMID 31048879, 2019). "We identified five candidates belonging to TRPA receptors including TRPA1, painless and three pyrexia genes." (PMID 31048879, 2019). "In wild-type and Trpa1−/−/Trpv1−/− mice, indomethacin reversed the pyrexia and normalized body temperature to the pre-yeast levels, indicating that these TRP channels are not involved in the antipyretic effects of cyclo-oxygenase inhibitors." (PMID 26227887, 2015). "While painless and pyrexia encode insect-specific TRPA-channels, TrpA1 and stj are conserved in humans." (PMID 21909389, 2011). "Similarly, the spatiotemporal expression patterns of TRPA1, painless, and pyrexia are at least partially different in the oriental fruit fly (Bactrocera dorsalis)." (PMID 32823776, 2020). "First is the TRPA homologues, including those related to TRPA1, painless, TRPA5, pyrexia, and waterwitch of insects, found in LF, dactyl, and brain." (PMID 30240423, 2018). "In a model of yeast induced pyrexia, administration of APAP evoked a marked hypothermia in wildtype and Trpv1−/− mice, but only restored normal body temperature in Trpa1−/− and Trpa1−/−/Trpv1−/− mice." (PMID 26227887, 2015).
Cough (5 papers, 2017 to 2025). A sudden, audible expulsion of air from the lungs through a partially closed glottis, preceded by inhalation. "This suggested that the TRPA1 signaling pathway in the skin effected cough exacerbation, following exposure to a cold environment." (PMID 32982765, 2020). "This provides a possible mechanism of how virus infection causes hypersensitisation in the airways and indicates that TRPV1, TRPA1 and ASIC3, or upstream events leading to their activation, are potential therapeutic targets for the treatment of virus-induced cough." (PMID 28187208, 2017).
cystic fibrosis (5 papers, 2016 to 2022). Autosomal recessive disorder caused by pathogenic variants in the CFTR gene (cystic fibrosis transmembrane conductance regulator), which encodes a chloride and bicarbonate channel expressed in epithelial cells, and follow the diagnosis criteria. "Studies demonstrated that the inhibition of TRPA1 results in a relevant reduction of the proinflammatory cytokines IL-1β and TNF-α in cystic fibrosis patients." (PMID 29682158, 2018). "Furthermore TRPA1 specific inhibitors from Hydra Biosciences (HC-030031) and Abbott (A-967079) inhibited P. aeruginosa induced transcription of IL8, IL1b, IL6 and tumor necrosis factor α (TNFα) in A549 and human cystic fibrosis cell line (CuFi-1)." (PMID 27827953, 2016).
fibrosis (5 papers, 2018 to 2025). the formation of excess fibrous connective tissue in an organ or tissue in a reparative or reactive process. "The underlying mechanism for the regulatory role of TRPA1 cardiac fibrosis remains elusive." (PMID 36103570, 2022). "In the present study, we focused mainly on M2-type macrophages as potential targets of TRPA1 in bleomycin-induced model of fibrosis." (PMID 36698198, 2023). "In order to reveal the potential mechanism and genetic signature of the accelerated cardiac fibrosis in older Trpa1-/- mice, we performed quantitative PCR array analyses of the mRNA expression of 84 fibrosis-related genes in the myocardial tissue." (PMID 36103570, 2022). "50% (3/6) of TRPM8 positive neurons expressed TLR5, 68.4% (13/19) of TRPV1 neurons expressed TLR5 and 62.5% (5/8) of TRPA1 expressed TLR5 in nodose/jugular ganglion in bleomycin induced fibrosis model." (PMID 29518161, 2018). "In DRG neurons, 41.2% (7/17) of TRPM8 positive neurons expressed TLR5, 59.1% (13/22) of TRPV1 neurons expressed TLR5 and 44.4% (4/9) of TRPA1 neurons expressed TLR5 in the bleomycin-induced fibrosis model." (PMID 29518161, 2018). "Following treatment with a TRPA1 inhibitor, AFM revealed a marked reduction in the elastic modulus of lung tissues from mice subjected to bleomycin-induced fibrosis, compared with that of untreated controls." (PMID 38635081, 2024). "To elucidate TRPA1’s involvement in IPF, we analyzed its expression in lung tissues from mice subjected to bleomycin-induced fibrosis." (PMID 38635081, 2024). "In the bleomycin-induced fibrosis model, 16.6% (1/6) of TRPM8 positive neurons expressed TLR2, 31.5% (6/19) of TRPV1 neurons expressed TLR2, and 12.5% (1/8) of TRPA1 expressed TLR2 in nodose/jugular ganglion." (PMID 29518161, 2018). "In the bleomycin-induced fibrosis model, 23.5% (4/17) of TRPM8 positive neurons expressed TLR2, 18.2% (4/22) of TRPV1 neurons expressed TLR2, and 44.4% (4/9) of TRPA1 neurons expressed TLR2 in the DRG." (PMID 29518161, 2018).
malaria (5 papers, 2013 to 2024). Malaria is a serious and sometimes fatal disease caused by a parasite that commonly infects a certain type of mosquito which feeds on humans. "A corresponding truncation had previously been shown to increase the expression levels of TRPA1 orthologs from man and malaria mosquito in P. pastoris, while retaining its ability to respond on activating stimuli." (PMID 38609906, 2024). "In fact, the TrpA1 genes in D. melanogaster and malaria-transmitting Anopheles gambiae were recently found to produce two transcript variants with distinct 5’ exons containing individual start codons." (PMID 27656903, 2016). "TRPA1 isoforms from malaria-transmitting mosquitoes, Anopheles gambiae (agTRPA1), were previously reported to be similar to their Drosophila counterparts in thermosensitivity." (PMID 27656903, 2016). "It is unclear precisely where these receptors, TRPA1 and GR19, are expressed in Aedes mosquitoes, but in the malaria-spreading mosquito Anopheles gambiae, TRPA1 is expressed at the tips of the antennae." (PMID 26670880, 2015). "However, most of the mosquito TRPA1 researches have been limited to Anopheles gambiae, the notorious malaria vector in West Africa9,10,15,16, and properties of TRPA1 channels of Anopheles stephensi, Aedes aegypti and Culex pipiens pallens are poorly characterized." (PMID 31882848, 2019). "This means that insect repellants that target nucleophile-sensitive TRPA1 could potentially repel malaria-transmitting mosquitoes without affecting other insect species." (PMID 27656903, 2016).
posttraumatic stress disorder (5 papers, 2022 to 2026). "Moreover, altered stress adaptation ability was observed in Trpa1-gene-deficient mice in a single prolonged stress model of posttraumatic stress disorder (PTSD)." (PMID 40574094, 2025). "Moreover, an altered stress adaptation capacity was observed in Trpa1 gene-deficient mice in the single prolonged stress model of posttraumatic stress disorder (PTSD)." (PMID 38339042, 2024). "Since UCN1 neurons are deeply implicated in stress-related disorders, we hypothesized that TRPA1/UCN1 neurons are also affected in posttraumatic stress disorder (PTSD)." (PMID 36561364, 2022). "Considering that a disturbed stress adaptation is characteristic for posttraumatic stress disorder (PTSD), we investigated the role of TRPA1 in this psychopathology." (PMID 36561364, 2022).